ATP11B (ATPase phospholipid transporting 11B (putative))
Diseases named in the same sentence as ATP11B in open-access papers (continued):
Sharing a sentence is not in itself a finding about the gene and the disease.
tumor (6 papers, 2022 to 2025). "In summary, we performed a genome-wide screening of metastatic repressors and identified ATP11b as a potent metastasis suppressor for Brca1-deficient cancers, as its knockout enhances tumor metastasis in vivo." (PMID 35025764, 2022). "ATP11b expression in Brca1-MT primary tumors was only 10% that in WT tumors as revealed by quantitative PCR (qPCR) and was much lower in lung metastatic tumor tissues." (PMID 35025764, 2022). "To validate the function of ATP11b in suppressing tumor metastasis in vivo, we implanted parental 545 cells and sgATP11b-545 cells into the mammary fat pad of nude mice." (PMID 35025764, 2022). "The data showed that the expression level of ATP11b in MT mammary glands was only 25% that in WT mammary glands and was even lower in tumor-adjacent mammary tissues." (PMID 35025764, 2022). "In the present study, by CRISPR/Cas9–mediated genome-wide screening, we identified ATP11b as a potent suppressor of tumor metastasis." (PMID 35025764, 2022). "Furthermore, LINC00606 can bind to protein ATP11B, which exerts anti-tumor effects in GBM, and affects the apoptosis level of GBM through the PI3K/AKT signaling pathway axis." (PMID 38725030, 2024). "When considering the expression of two genes, ATP11B and PTDSS2, simultaneous low ATP11B expression and higher PTDSS2 expression are associated with worse prognoses compared to patients with higher ATP11B and lower PTDSS2 expression in the tumor." (PMID 39409074, 2024). "In addition, the expression of ATP11B was negatively correlated with that of LINC00606 in GBM patient’s tumor samples." (PMID 38725030, 2024). "In contrast, ATP11B depletion largely suppressed tumor growth in immunocompetent C57BL/6 mice." (PMID 35288467, 2022). "Next, we investigated the mechanism by which the disruption of ATP11b enhances tumor metastasis." (PMID 35025764, 2022). "Interestingly, LTX-315-induced tumor growth inhibition was largely abolished by ATP11B depletion." (PMID 35288467, 2022). "Moreover, we also found reduced expression of ATP11b in Brca1-MT mammary glands compared with WT glands, and it was even lower in tumor tissues, suggesting that Brca1 might play a role in maintaining ATP11b expression." (PMID 35025764, 2022). "Overall, the LINC00606/miR-486-3p/TCF12/ATP11B axis is involved in the regulation of GBM progression and plays a role in tumor regulation at transcriptional and post-transcriptional levels primarily through LINC00606 sponging miR-486-3p and targeted binding to ATP11B." (PMID 38725030, 2024). "Consistently, no inhibitory effect on tumor growth was observed in the immunodeficient nude mice after the depletion of ATP11B." (PMID 35288467, 2022). "In another study, analysis of the cells from breast cancer patients demonstrated that no or low expression of ATP11B in conjunction with high expression of PTDSS2, which is negatively regulated by BRCA1, markedly accelerates tumor metastasis and associates with poor prognosis." (PMID 37686603, 2023). "In contrast, mixed expression patterns of these genes were observed in the nonresponders, and most nonresponders (11/12) had tumor cell infiltration into their lymph nodes and expressed either high ATP11B or high N-cadherin protein levels, showing that they were not sensitive to drug treatment." (PMID 35025764, 2022). "In this study, we demonstrated that no expression or low expression of ATP11B in conjunction with high expression of PTDSS2, which was negatively regulated by BRCA1, markedly accelerates tumor metastasis." (PMID 35025764, 2022).
cancer (5 papers, 2022 to 2024). A tumor composed of atypical neoplastic, often pleomorphic cells that invade other tissues. "The influence of ATP11B on cancer cell immune surveillance was traced to its control over the trafficking of PD-L1, which was mislocalized to the lysosome and degraded in ATP11B deficient cells." (PMID 38382846, 2024). "Previous studies have shown that the candidate protein ATP11B is an inhibitor of cancer metastasis and displays heterogeneous expression in various nerve cell-s in the brain." (PMID 38725030, 2024). "Atp11b has been reported to be closely related to cancer, neurological diseases, cell morphology, and other diseases." (PMID 39062857, 2024). "Our further analysis revealed that in Brca1-WT cancer cells, ATP11b and Ptdss2 signaling also plays similar roles in cancer metastasis." (PMID 35025764, 2022). "Therefore, LTX-315, or the development of ATP11B-targeting drugs, might improve the efficacy of cancer immunotherapy." (PMID 35288467, 2022).
neurological diseases (3 papers, 2022 to 2025). "The abnormal expression and mutation of proteins belonging to the P4-ATPase family, including Atp11b, results in a variety of neurological diseases." (PMID 35741595, 2022). "Consequently, ATP11B presents a promising avenue for the development of treatments for neurological diseases, such as AD." (PMID 40123832, 2025).
ATP11B also shares sentences with these, for which no sentence is quoted: acute myeloid leukemia (1 paper); adrenocortical carcinoma (1); Alzheimer disease (1); bronchial hyperreactivity (1); cerebral small vessel disease (1); endothelial dysfunction (1); gastroenteritis (1); Hyperkeratosis (1); infection (1); lung squamous cell carcinoma (1); metastatic tumors (1); Parkinson’s (1); septic shock (1).